RTL8B (retrotransposon Gag like 8B)
Synonyms: CXX1C; FAM127C; MAR8B; SIRH4
Tractability: PROTAC: ubiquitination databases record sites on it.
Gene: Protein-coding gene on chromosome X (135,020,513 to 135,022,542, reverse strand). Ensembl gene ENSG00000212747.
Gene Ontology:
Molecular function: protein binding
Homologues: Orthologues: mouse Rtl8a (71% identical), mouse Rtl8b (71% identical), rat Rtl8a (71% identical), mouse Rtl8c (61% identical). Paralogues in human: RTL8A (96% identical), RTL8C (93% identical), LDOC1 (58% identical), RTL6 (35% identical), RTL3 (33% identical), PEG10 (32% identical), RTL5 (31% identical), RTL1 (30% identical), RTL10 (27% identical), RTL4 (11% identical).